MMP2 (matrix metallopeptidase 2)
Diseases named in the same sentence as MMP2 in open-access papers (continued):
Sharing a sentence is not in itself a finding about the gene and the disease.
liver fibrosis (continued). "CSE might also modify elements related to ECM degradation or turnover, because caffeine decreased MMP‐2 and MMP‐9 activity in a rat model of liver fibrosis, and cocoa procyanidins inhibited the expression and activation of MMP‐2 in human vascular SMCs." (PMID 40321100, 2025). "In a TAA-induced liver fibrosis model, EVs isolated from adipose tissue-derived MSCs (ADSCs-EVs) significantly suppressed the expression of fibrogenic markers, including MMP-2, collagen-1, and α-SMA, while accumulating in fibrotic liver tissue to restore liver functionality." (PMID 40852596, 2025). "The expression levels of various proteins, specifically PIK3CB, AKT, pAKT, HDAC3, HDAC6, MMP9, MMP2, VIM, and α-SMA, which are implicated in hepatocyte degeneration as well as the initiation and progression of liver fibrosis, were analyzed using Western blotting." (PMID 39683581, 2024). "In liver fibrosis, MMP-2 has a profibrogenic role and is highly expressed in myofibroblasts." (PMID 37371866, 2023). "Abdel-Latif studied plasma MMP2 in 15 cases of liver fibrosis with HCV RNA detection, 10 cases of liver cirrhosis with HCV, and 15 age-matched and gender-matched control subjects and found that MMP2 could be used as a prognostic marker for liver fibrosis." (PMID 35342754, 2022). "However, an increase in proMMP-2, and also to a lesser extent active MMP-2, suggests a continuous rotation of the active matrix even in advanced liver fibrosis." (PMID 36232681, 2022). "In addition, western blot and qRT-PCR analysis showed that deficiency of Airn significantly promoted the upregulation of CCl4-induced α-SMA, COL1α1, MMP2, and TIMP1, suggesting Airn deficiency aggravated CCl4-induced liver fibrosis." (PMID 36171606, 2022). "Indeed, MMP2 is significantly upregulated in activated HSCs during liver fibrosis progression, regulating the degradation of the normal liver matrix and further promoting LF." (PMID 35465330, 2022). "Hence, it is surmised that the LV extract can ameliorate liver fibrosis by regulating an MMP-2-related pathway, although further studies are needed to verify this mechanism." (PMID 33494735, 2021). "It is speculated that MMP-2 promotes the formation and development of liver fibrosis, mainly through the regulation of the activation, proliferation, and migration of HSCs." (PMID 33933107, 2021). "In the present study, the effects of L‐THP treatment on HSCs activation and ECM production in liver fibrosis were assessed by determining mRNA and protein expressions of Col‐1, α‐SMA, TIMP1 and MMP2 in the liver tissues from the two different liver fibrosis models." (PMID 33438347, 2021). "Although we did not study the effects on liver fibrosis, we hypothesize that GTE might ameliorate the hepatic fibrosis induced by overfeeding via the downregulation of MMP2 expression." (PMID 31500159, 2019). "Furthermore, the IGFBPrP1 knockdown attenuated liver fibrosis by re-establishing the MMP2/TIMP2 and MMP9/TIMP1 balance concomitant with the inhibition of HSCs activation and degradation of the ECM." (PMID 30769840, 2019). "The overexpression of MMP2 also leads to the over-activation of HSCs, initiating hepatic fibrosis." (PMID 31409055, 2019). "It is well known that at the early stage of hepatic fibrosis, the expression of MMP-2 is very high." (PMID 31847284, 2019). "In particular, the level of MMP-2 has been reported to be increased in liver fibrosis." (PMID 31847284, 2019). "MMP2 is a known gelatinase that is capable of degrading type IV collagen and is also one of the noninvasive biochemical markers of chronic liver diseases such as liver fibrosis." (PMID 31500159, 2019). "MMP2 acts as a collagenase, known to be activated during hepatic fibrosis." (PMID 30670377, 2019). "MMP-2 (gelatinase A) is a type of collagenase that involves the metabolism of type IV collagen in the basement membranes and hereby closely plays a role in the development of hepatic fibrosis." (PMID 29853950, 2018).
liver fibrosis (continued). "In addition, increased expression and activity of MMP-2 are one of the main causes of liver fibrosis, while EGCG can reduce its activity and possess the antifibrosis effect via downregulation of the expression of MMP-2 mRNA." (PMID 28884125, 2017). "Liver fibrosis improved upon administration of OM, as assessed by reduced deposition of collagen and reduced expression of genes co-occurring with liver fibrosis, such as MMP-2, TIMP-1, and type I procollagen." (PMID 26941644, 2016). "In this research, c-fos (a member of AP-1), P65 (a member of NF-κB), and TGF-β1 were increased markedly during the initiation of hepatic fibrosis, which might enhance the expression of MMP-2 and MMP-9." (PMID 27739503, 2016). "The upregulation of MMP-2 gene expression may be a compensatory response to the excessive accumulation of ECM during liver fibrosis, which has been observed by other authors." (PMID 27594891, 2016). "The potential role of MMP-2 for prognosis of liver fibrosis remains unclear, due to contradictory data was reported in different studies." (PMID 26464613, 2015). "The present study was designated to correlate the levels of MMP-2, MMP-9 and TNF-α with the pathogenesis of chronic liver diseases (CLD) caused by HCV, it also aimed at using them as possible non-invasive serum markers for liver fibrosis." (PMID 26464613, 2015). "Matrix metalloproteinase-2 (MMP-2) may be involved in the formation and reversal of hepatic fibrosis." (PMID 26017616, 2015). "Furthermore, increased ColIα1 expression was also observed in the BDL model, suggesting that MMP-2 plays a similar role in different forms of liver fibrosis." (PMID 24713275, 2014). "If the expression and activity of MMP-2 were interfered at different stages, the progression of liver fibrosis may be changed." (PMID 21731450, 2011). "The aim of this work was to develop a novel competitive enzyme-linked immunosorbent assay (ELISA) for measuring MMP-2 and MMP-9 mediated turnover of type VI collagen and to measure the neo-epitopes in two complementary experimental models of liver fibrosis induced by BDL or CCl4." (PMID 21935455, 2011). "During the progression of liver fibrosis, deposition of type IV collagen increases significantly, which might be due to the inability of MMP-2 to degrade type IV collagen." (PMID 21731450, 2011). "In addition, our previous studies have shown that hypoxia stimulated MMP-2 synthesis in HSCs in vitro, and the expression of hypoxia inducible factor-1α was increased in hepatocytes in the rat liver fibrosis tissues." (PMID 21731450, 2011). "Subsequently, transcript levels of genes associated with hepatic fibrosis were assessed via qRT-PCR, which revealed a significant upregulation of fibrosis-related transcripts encoding proteins such as procollagen α1(I), TIMP-1, α-SMA (ACTA2), MMP-2, and MMP-9 in the livers of scurfy mice." (PMID 37818371, 2023). "The present study shows that Mmp2 expression increases in liver fibrosis, however, Pttg1 interference may have an antifibrogenic effect also by reducing Mmp2 expression and, consequently, by blocking degradation of normal perisinusoidal matrix and promoting activation of quiescent HSC." (PMID 35050550, 2022). "Similarly, the gene coding for the ECM modifying enzyme MMP2 and tissue inhibitor of MMPs-2 (Mmp2, Timp2), which respectively exert anti- and pro-fibrogenic roles in liver fibrosis, were strongly upregulated by CCL4 treatment in both Nlrc5-/- and control mice livers." (PMID 34712238, 2021). "Therefore, agents proved to be potent inhibitors of MMP-2 may be beneficial for hepatic fibrosis treatment." (PMID 31847284, 2019). "Moreover, miR-200b appears to enhance expression of matrix metalloproteinase-2 (MMP-2), which may increase the migration of HSCs during liver fibrosis progression." (PMID 28538690, 2017).
liver fibrosis (continued). "Alternatively, elevation of these mRNA might be accompanied with acute liver injury because MMP-13 was reported to express in CCl4-induced acute liver injury, and because expression of MMP-2 was reported to increase in the aggressive phase of liver fibrosis but decrease in the repair stage." (PMID 27547834, 2016). "Interestingly, inhibition of IL—6 signaling can induce liver fibrosis by induction of MMP-2." (PMID 25789991, 2015). "However, whether MMP-2 has an effect on the formation of hepatic fibrosis by directly examining hepatic stellate cells (HSCs) remains to be elucidated, and no clinical antifibrotic drugs based on MMP-2 have been approved for preventing fibrosis." (PMID 26017616, 2015). "Similar to increased liver fibrosis in Mmp2−/− mice, Takamiya and colleagues demonstrated increased collagen deposition and fibroblast activation – as indicated by αSMA production – in diabetic Mmp2−/− mice, supporting the view that MMP-2 has an anti-fibrotic role." (PMID 24713275, 2014). "Furthermore, in experimental murine models it has been shown that mast cells could play a role in the pathogenesis of liver fibrosis and may contribute to the degradation of fibrosis by synthesizing and secreting matrix metalloproteinase-2 (MMP-2)." (PMID 24084730, 2013). "Moreover, MMP-2 appears to also have a protective role in mouse models of liver fibrosis by inhibiting collagen I synthesis and suppressing TIMP-1 upregulation which could thus contribute to lower fibrosis in MMP19KOs." (PMID 23056273, 2012). "A clear repression in hepatic fibrosis was observed in CeO2NP-treated groups as demonstrated by significant downregulation in TGF-β1 and p-Smad 2 and 3 proteins and COL1A1, MMP-2, and α-SMA expressions in hepatic tissues." (PMID 40679589, 2025). "Existing research has demonstrated that changes in the secretion levels of IV Col and HA, as well as the gene expression of MMP2 and MMP9 in BRL-3A cells, can reflect liver fibrosis in the body to a certain extent." (PMID 40667449, 2025). "In TAA-induced liver fibrosis, quercetin decreased liver fibrosis index via provoking HSC apoptosis, and down-expression of MMP-9 and MMP-2." (PMID 40892759, 2025). "The study showed that betaine modulates the antifibrogenic effects of MIF in TAA-induced liver fibrosis, by decreasing TGF-β1, PDGF-BB, MMP-2, MMP-9, TIMP-1, and the deposition of ECM (Coll1 and Coll3) in the liver." (PMID 38927544, 2024). "Corroborating the cardiac findings, in a model of nonalcoholic steatohepatitis, IL-11 inhibition by X203 or X209 decreased liver fibrosis by suppressing ERK activation and consequently MMP2 and TIMP1." (PMID 38392279, 2024). "Specifically, FDP alleviated liver fibrosis by reducing the levels of COL/A, TGF-β, α-SMA, and MMP-2 in FFC diet-induced MASLD mice." (PMID 39519593, 2024). "This is evidenced by the observed suppression of established hepatic fibrosis markers, including type I and IV collagen, TIMP-1, and MMPs (MMP-2 and MMP-9)." (PMID 39201682, 2024). "Similar to our results, upregulation of MMP2 and MMP14 together with upregulation of TIMP1 has been shown in liver fibrosis." (PMID 38990974, 2024). "Taken together, these data suggested that ANTXR2 is the key factor regulating the activity of MMP2 in ECs, and that endothelial ANTXR2 plays a protective function in liver fibrosis." (PMID 38322497, 2023). "Pre-symptomatic results from carbon tetrachloride-induced hepatic fibrosis in rat models treated with anti-TIMP1 antibody revealed accumulation of fibrosis, decreased HSC activation, as well as reduced MMP2 activity." (PMID 36985782, 2023). "Matrix metalloproteinases (MMPs), particularly MMP-2 and MMP-9, are upregulated in activated HSCs, which are pivotal to cell migration and responsible for liver fibrosis." (PMID 37034499, 2023). "The inhibitory effect of α-mangostin on liver fibrosis markers was also demonstrated by the mRNA levels of α-SMA, col1a2, MMP2 and desmin." (PMID 37760177, 2023).
liver fibrosis (continued). "EPCs transplantation activated HGF-mediated hepatocyte proliferation and increased sinusoidal blood vessel density by secreting higher MMP-2 and VEGF in carbon tetrachloride-induced liver fibrosis." (PMID 35883127, 2022). "In contrast, in experimental liver fibrosis, MMP-2 KO mice responded with increased fibrotic remodeling, while inhibition of MMP-2 attenuated experimental kidney fibrosis." (PMID 35804363, 2022). "RT-PCR and WB analyses indicated that liver fibrosis-related factors (including α-SMA, TGF-β1, TIMP-1, MMP-2, and Vimentin) were significantly downregulated, while E-cadherin was significantly upregulated in wild-type and αERKO mice after SSd treatment." (PMID 35694250, 2022). "There were some literatures about MMP2 and MMP9 related to liver fibrosis, such as MMP9 was up-expressed in HCV patients with different stages of fibrosis, the activity of MMP2 and MMP9 in patients with liver cirrhosis were increased and so on." (PMID 34301291, 2021). "The results showed that levo‐tetrahydropalmatine alleviated liver fibrosis by inhibiting the formation of extracellular matrix (ECM) and regulating the balance between TIMP1 and MMP2 in the two mice liver fibrosis models and cell model." (PMID 33438347, 2021). "The levels of FN, collagen-I, collagen-III, collagen-IV, MMP-2 and MMP-9, which have been recognized to be as markers for liver fibrosis, were also analyzed by Western blot assay in HG-challenged HSC-T6 cells following captopril treatment." (PMID 34607529, 2021). "We also studied FN, collagen-I, collagen-III, collagen-IV, MMP-2 and MMP-9 levels, which are markers for liver fibrosis." (PMID 34607529, 2021). "In the family of MMPs, MMP2 and MMP9 are particularly important for the development of liver fibrosis since they degrade type IV collagen (basal membrane)." (PMID 34301291, 2021). "Magnesium chenoursodeoxycholic acid (Mg-CUD) suppression increases MMP-2 and tissue inhibitor of MMP-1 mRNA expression, as well as levels of NF-κB, TNF-α, IL-6, and COX-2 in carbon tetrachloride-induced liver fibrosis in rats." (PMID 34220502, 2021). "Several studies revealed that 25–300 mg/kg EGCG attenuated CCl4-induced liver fibrosis partially through inhibiting HSC activation and targeting MMP-2 via the modulation of membrane type 1-MMP activity." (PMID 33082829, 2020). "Overall, treatment with the miR-150 secretome reduced the expression of profibrogenic markers, such as α-SMA, MMP2, and TGF-β, more than that of the control secretome in both in vitro and in vivo models of liver fibrosis." (PMID 32152450, 2020). "MMP2 and TIMP1, as representative cytokines to study the process of liver fibrosis, can participate in the progress of liver fibrosis." (PMID 32463570, 2020). "Previous studies have shown that FIS supplementation prevents hepatic fibrosis by suppressing the gene expressions of COL1, MMP2, MMP3, and MMP9 and collagen accumulation." (PMID 33381023, 2020). "In a rat model with bile duct ligation induced hepatic fibrosis, MMP-2 and MMP-9 activities has been demonstrated to increase within 2 days post ligation therefore, MMP-2 and MMP-9 are considered to be suitable markers for the onset of liver fibrosis." (PMID 31653214, 2019). "The expressions of MMP-2 (known as gelatinase-A) and MMP-9 (known as gelatinase-B) are significantly upregulated in liver fibrosis for ECM remodeling." (PMID 31847284, 2019). "Recently, an increase of pro-MMP-2 accompanied by increased TIMP-1 and TIMP-2 levels in NAFLD liver fibrosis has been reported." (PMID 30769840, 2019). "We further analyzed MMP-2, MMP-9, MMP-13 and tissue inhibitor of matrix metalloproteinases 1 (TIMP-1) hepatic gene expressions after BDL- and CCl-4-induced liver fibrosis using RT-PCR." (PMID 30875826, 2019). "Hamsters that fed on HFD showed high levels of MMP2 and MMP9 in the liver, increase in these MMPs in liver generally correlates with liver fibrosis." (PMID 31653214, 2019).
liver fibrosis (continued). "In the late post infection, the expression of MMP2 decreases gradually, and the ECM deposits in large quantities and hepatic fibrosis further develops." (PMID 31409055, 2019). "NASH mice displayed decreased HO-1 levels and HO activity, increased levels of hepatic heme, NOV, MMP2, hepcidin, and increased NAS scores and hepatic fibrosis." (PMID 30057822, 2018). "In conclusion, PS-modified NLCs nanoparticles prolonged the retention time of Cur, and enhanced its bioavailability and delivery efficiency to the livers, resulting in reduced liver fibrosis and up-regulating hepatic expression of HGF and MMP-2." (PMID 29214887, 2018). "The ratio of matrix metalloproteinase-2 (MMP2) and its inhibitor TIMP2 has been found to be imbalanced in hepatic fibrosis whereas MMP-9/TIMP-1 ratio is dysregulated in liver metastasis." (PMID 30087389, 2018). "Downregulation of MMP2 expression and the TGF-β1/Smad signaling pathways can relieve liver fibrosis in rats." (PMID 28335383, 2017). "We have previously shown that sinusoidal angiogenesis driven by myeloid cell-derived VEGF along with upregulation of MMP-2 and MMP-14 in sinusoidal endothelial cells is required for the resolution of liver fibrosis." (PMID 28118605, 2017). "In a rat model of hepatic fibrosis induced by bile duct ligation (BDL), MMP-2 and MMP-9 were increased suggesting that continued tissue damage and inflammation induced MMP expression." (PMID 28086769, 2017). "It has been known that the expression levels of MMP2, MMP9, TIMP1 and TIMP2 mRNAs are increased in the patients with hepatic fibrosis." (PMID 26863419, 2016). "In conclusion, MMP2, MMP9 and TNF-α showed high reproducibility to differentiate patients with liver fibrosis (F1–F4) from control group." (PMID 26464613, 2015). "MMP2, MMP9 and TNF-α showed a significant elevation in patients with liver fibrosis (F1–F4) compared to control group (p=0.001)." (PMID 26464613, 2015). "In liver fibrosis in both human and mouse tissue MMP expression and activity (MMP-2, -9, -13 and -14) increased with progressive injury and localised to hepatocytes." (PMID 25076423, 2014). "Consistent with a previous study in mice fed the MCD diet, expression levels of MMP-2, MMP-13, TIMP-1, and TIMP-2 were increased in mice with MCD diet-induced hepatic fibrosis in this study." (PMID 24066058, 2013). "We demonstrated that PPARα agonist significantly repressed hepatic expression of visfatin, and consequently reduced PI3K, MMP-2 and MMP-9 expression, thus suppressing the progression of ethanol mediated liver fibrosis." (PMID 23388073, 2013). "The aim of this study was to develop an ELISA detecting a fragment of type VI collagen generated by MMP-2 and MMP-9, and evaluate this assay in two preclinical models of liver fibrosis." (PMID 21935455, 2011). "In hepatic fibrosis, there is an increase in MMP-2 (collagenase IV or gelatinase A) leading to increased collagen IV destruction." (PMID 27942306, 2010). "Evidences point to a central role for osteopontin in liver fibrosis as it induces hepatic stellate cell (HSC) migration and proliferation and stimulates synthesis of matrix metalloproteinase 2 (MMP-2) and type I collagen by HSC." (PMID 18590516, 2008). "Furthermore, we examined the relative mRNA expression levels of key markers related to hepatic fibrosis (Acta2, Cola2, TGF-β1, and MMP2), cirrhosis (CXCR4, SOX9, DCN, and MFAP4), and cancer (Bcl2, CDKN2a, c-Myc, and Fn1) across the experimental groups." (PMID 39851554, 2025). "In addition, liver lipid synthesis markers (FAS) and hepatic fibrosis markers (such as TGF‐ꞵ, α‐SMA, and MMP2) were increased in the WD‐treated group, but these elevations were significantly decreased by the oral administration of both PNVs and EA." (PMID 40212474, 2025).